IRF3 (interferon regulatory factor 3)
Diseases named in the same sentence as IRF3 in open-access papers (continued):
Sharing a sentence is not in itself a finding about the gene and the disease.
Insulin resistance (continued). "The manipulation of TLRs that lay upstream of IRF3 was found to influence insulin resistance in murine adipocytes whereas the knockdown of IRF3 abolished insulin resistance." (PMID 35088922, 2022). "It was shown that activation of TLR4/IRF3 signaling pathways results in insulin resistance in murine adipocytes." (PMID 33050324, 2020). "Adipose IRF3 expression was found to be elevated in obese mice and humans and IRF3 knockdown prevented insulin resistance." (PMID 31718015, 2019). "For example, both FGF21 and AKT1S1 (also known as PRAS40) are substrates for phosphorylation by AKT kinase, and effect fatty liver disease, while IRF3 mediates HFD-induced insulin resistance and impaired hepatic glucose metabolism trough a mechanism involving AKT." (PMID 39060446, 2024). "To determine whether IRF3 is required for LPS-induced insulin resistance, we knocked down IRF3 in mature adipocytes using a doxycycline-inducible lentivirus." (PMID 38816388, 2024). "However, in 3T3-L1 adipocytes, IRF3 contributed to insulin resistance induced by TLR ligands, while IRF3 knockout improved glucose homeostasis by enhancing glucose uptake and increasing GLUT4 expression and insulin signaling in adipose tissue." (PMID 39669992, 2024). "Studies showed that IFNβ may limit HSC activation and reduction in IRF3 activation may lead to hepatic insulin resistance and steatosis, which contradicted with the phenotype of our HFHF model." (PMID 37605246, 2023). "Moreover, insulin resistance and proteolysis are re‐induced by Irf3 overexpression under Tlr13 deletion." (PMID 35088922, 2022). "In addition, activation of the STING downstream signaling molecule IRF3, whose expression is highly induced in adipocytes of obese mice and humans, led to insulin resistance in adipocytes." (PMID 34665236, 2021). "High-fat fed adipocyte-specific Irf3 deficient (FI3KO) mice studied at thermoneutrality exhibit improved insulin and glucose tolerance, while adipocyte-specific overexpression of Irf3 (FI3OE) promotes glucose intolerance and insulin resistance on HFD, also in a weight-independent manner." (PMID 38816388, 2024). "IRF3 attenuates steatosis and insulin resistance by constraining IKKβ/NF-κB activity, and IRF7 is induced downstream of IRF3-dependent IFN-λ/IFN-β programs during viral or sterile stress." (PMID 41614922, 2026). "And ablation of IRF3 in mice reduced HFD-induced macrophage infiltration into fat pads, inflammatory gene expression, and insulin resistance." (PMID 39183465, 2024). "Studies have demonstrated that IRF3, part of the cGAS-STING pathway, plays a protective role against diet-induced hepatic insulin resistance." (PMID 39669992, 2024). "A RIKA-like activity of IRF3 controls HFD-induced hepatic steatosis and insulin resistance, in which IRF3 interacts with IKKβ to suppress hepatic inflammatory responses." (PMID 37515265, 2023). "Consistently, TLR3 and TLR4, upstream of interferon regulatory factor 3 (IRF3) signalling, induce insulin resistance and thermogenesis in adipocytes." (PMID 36119080, 2022). "On the other hand, ablation of IRF3 in mice reduced HFD-induced macrophage infiltration into fat pads, inflammatory gene expression, and insulin resistance." (PMID 34665236, 2021). "IRF3 promotes HFD‐induced adipose tissue inflammation and insulin resistance." (PMID 39158380, 2025). "IRF3 knockout reduced the phosphorylation of residue Tyr608 in insulin receptor substrate 1 (IRS1) and the phosphorylation of protein kinase B (AKT) in the livers of HFD-fed mice, further aggravating HOMA-IR and insulin resistance." (PMID 38164186, 2024). "Furthermore, mice lacking IRF3 are protected from diet-induced insulin resistance and systemic inflammation." (PMID 33050324, 2020). "Mice lacking IRF3 showed reduced insulin receptor substrate 1 (IRS1) and protein kinase B (AKT) phosphorylation in the liver, worsening insulin resistance." (PMID 39669992, 2024).
influenza (24 papers, 2011 to 2026). An acute viral infection of the respiratory tract, occurring in isolated cases, in epidemics, or in pandemics; it is caused by serologically different strains of viruses (influenzaviruses) designated A, B, and C, has a 3-day incubation period, and usually lasts for 3 to 10 days. "These diseases encompass herpes simplex encephalitis (HSE) and severe influenza in IRF3- and IRF7/IRF9 deficiency, respectively." (PMID 30671054, 2018). "A dysfunction of IRF3/7 as main mediators of the type I and III interferon response have been described to be associated with increased morbidity and mortality in influenza infected mice." (PMID 31067687, 2019). "It is unclear how influenza infection of Calu-3 cells pretreated with IFN-λ1 can select for a virus that induces less IRF3 phosphorylation and a consequent weaker production of IFN-λ1." (PMID 28750037, 2017). "We propose that DMXAA can be used as an adjuvant that targets a specific innate immune signaling pathway via IRF3 for potential applications including vaccines against influenza which requires a high safety profile." (PMID 23555875, 2013). "Visualizing these DEGs at 24 hpi, using the “Role of Hypercytokinemia and Hyperchemokinemia in the Pathogenesis of Influenza” pathway, predicts that robust antiviral gene modulation could be through IRF3/IRF7 and other mediators of ISGF3." (PMID 38932231, 2024). "Moreover, a recent study in humans administered with live attenuated influenza vaccine and S. pneumonia reported that expression of IL-1β was reduced, whereas expression of the IRF3/IFN-β-driven cytokine IP-10 was increased." (PMID 37435074, 2023). "Therefore, the expression of IRF3 and NF-κB in lung tissue was examined to further investigate the protective mechanism of vitamin C on influenza." (PMID 25710018, 2015). "Therefore, we determined the level of phosphorylated IRF3 in influenza H7N9-infected cells." (PMID 36329446, 2022). "In contrast, influenza patients showed activation of STAT3 and nuclear factor kappa-light-chain enhancers of activated B-cells (NF-kappa-beta) pathways instead of STAT1/IRF3." (PMID 38542251, 2024). "The anti-influenza effects of LBO may be attributed to the reduction of proinflammatory cytokines and the blocking of P65 and IRF3 activation." (PMID 34497658, 2021). "The exact mechanism of OASL induction by de novo KSHV infection or reactivation is not known, but OASL is induced by Sendai and influenza infection in an IRF3-dependent manner." (PMID 29499066, 2018). "While it is clear that both VSV and influenza infections can involve TLR4, the cytosolic nucleic acid innate immune receptors play a large role in detecting RNA viruses and initiating an IFN response via the TBK-1/IRF3 axis." (PMID 23853595, 2013). "Here, employing a multi-omics strategy encompassing in vitro assays, in vivo influenza A virus (IAV) infection models, NanoString, transcriptomic analyses, and scGPT-based computational modeling, we dissect the divergent and context-dependent roles of irf3 and irf7." (PMID 41694598, 2026). "Finally, there are some remaining pieces to the puzzle, since the infectious phenotype of patients with mutations in IRF3 and STAT1 that impair induction and responsiveness to type I IFN, respectively, have not revealed a similar increased risk of severe influenza infection." (PMID 30671054, 2018). "We also show that between the two transcription factors IRF3 and IRF7 implied in IFN induction, IRF3 is of less importance than IRF7, but complete abolition of influenza-triggered IFN expression is seen only in the absence of both molecules." (PMID 24278020, 2013).
systemic lupus erythematosus (19 papers, 2010 to 2026). An autoimmune multi-organ disease typically associated with vasculopathy and autoantibody production. "Loss of function mutations in TREX1 and gain-of-function mutations of IFIH1 are both known to cause lupus-like phenotypes in humans and animal models, while both are involved in the pathways that activate IRF3." (PMID 32719713, 2020). "While IRF1, IRF3, IRF5, and IRF8 predominantly exacerbate AS, context-dependent roles (e.g., IRF5 in lupus-associated AS) highlight their therapeutic complexity." (PMID 40980176, 2025). "While the loss of IRF3 solubility in PISA was not statistically significant, we observed increased phosphorylation of IRF3 in dendritic cells from peripheral blood of Ncf1‐mutant mice in the spontaneous lupus model." (PMID 39120068, 2024). "TNF is already targeted by biologic therapeutic approaches, and IFN regulatory factors 3 and 7 (IRF3 and IRF7) have been implicated in the IFN signature in lupus previously." (PMID 27846842, 2016). "Indeed, the significance of the IRF-3 pathway has been reported for inflammation-related diseases such as rheumatoid arthritis, systemic lupus erythematosus, systemic sclerosis, inflammatory bowel disease, chronic obstructive pulmonary disease, and type II diabetes." (PMID 29751576, 2018). "Numerous studies have demonstrated that the expression and activation of IRF family members, including IRF3, IRF5, and IRF7, are significantly increased in systemic autoimmune diseases such as systemic lupus erythematosus (SLE) and Sjögren’s syndrome (SS)." (PMID 41383611, 2025). "The importance of interferons was highlighted in our previous results on the TLR4 signaling pathway, where TLR4, TICAM1, TICAM2, TBK1, IRF3, IFNA1, and IFNA2 mRNAs showed changes in the murine lupus-like models." (PMID 29349090, 2017). "IRF3 promoter SNPs were first described in patients with systemic lupus erythematosus (SLE)." (PMID 20886096, 2010). "As increasing evidence links the PRR/TBK1/IRF3 axis to autoimmune disease (including systemic lupus erythematosus [SLE]), vaccine responses, and the development of malignancy, the identification of regulators of this pathway may reveal novel therapeutic targets." (PMID 31346090, 2019). "Indeed, given the central role for IRF3, 5, and 7 in regulating IFN expression, it is not surprising that they have been implicated in diseases such as systemic lupus erythematosus (SLE), which are driven in part by overexpression of type I IFNs." (PMID 30984161, 2019).
gastric cancer (18 papers, 2017 to 2025). A primary or metastatic malignant neoplasm involving the stomach. "Meanwhile, recent studies have shown that the expression of IRF3 is positively correlated with that of Yes‐associated protein (YAP) in gastric cancer." (PMID 37032635, 2023). "IRF3 was previously implicated as an agonist of YAP and IRF3 was positively correlated with YAP in gastric cancer." (PMID 33292210, 2020). "While earlier studies established HBP21 as a tumor suppressor in hepatocellular and gastric carcinomas, recent work revealed its involvement in innate immunity, where it enhances interferon regulatory factor 3 (IRF3) activation during antiviral responses." (PMID 40757051, 2025). "Meanwhile, downregulation or overexpression of IRF3 in human gastric carcinoma cell lines BGC-823 and HGC-27 did not affect the Wnt target or associated genes expression upon wnt3a treatment." (PMID 33188184, 2020). "Furthermore, Sophoridine also polarized tumor-associated macrophages (TAMs) to M1-TAMs through TLR4/IRF3 axis and thus enhanced the cytotoxic function of CD8+ T cells in gastric cancer microenvironment in a recent report." (PMID 32571331, 2020). "The expression of IRF3 is up-regulated and prognosticates patient survival in gastric cancer." (PMID 33006365, 2020). "Recently, we discovered that IRF3, a central transcription factor in antiviral innate immunity, acts as an agonist of YAP-TEAD in gastric cancer and that pharmacological inhibition of IRF3 by amlexanox suppresses YAP-driven gastric tumor growth." (PMID 36008411, 2022). "Treatment with amlexanox that decreases the activity of IRF3, significantly suppresses YAP-driven gastric cancer growth in mice." (PMID 31225446, 2017). "In this regard, we have recently found that both IRF3 and YAP are unregulated in clinical samples of gastric cancer." (PMID 31225446, 2017). "Another agent is Sophoridine which has been reported to suppress M2 polarization and increase M1 polarization through TLR4/IRF3 pathway and inhibit TAMs infiltration by downregulating CCR2 expression in gastric cancer TME, thereby improving the cytotoxicity function of CD8 + T cells." (PMID 39003350, 2024). "Moreover, these virus-induced signals increase the expression of IRF3 (Interferon Regulatory Factor 3), a key regulator of innate immunity, which binds to YAP/TEAD4 complex and upregulates YAP target genes in gastric cancer." (PMID 35602596, 2022). "Targeting IRF3, which was shown to be a YAP agonist target against gastric cancer, may work similarly in MESO." (PMID 34768716, 2021). "The expression of TP53BP1 positively correlated with the expression of cGAS, STING, and IRF3, while the expression of FANCD2 positively correlated with the expression of IRF3 and STAT6, suggesting the major role of DDR in SASP activation in early gastric cancers." (PMID 36061145, 2022).
breast carcinoma (16 papers, 2020 to 2026). "The protein levels of p‐AKT1 and nuclear IRF3 in 349 ER+HER2– breast cancer samples were evaluated by IHC." (PMID 39023171, 2024). "We then assessed the clinical significance of p‐AKT1 and nuclear IRF3 in ER+ HER2– breast cancer patients who received adjuvant endocrine therapy." (PMID 39023171, 2024). "Mechanistically, hyperactivated AKT1 blocked the formation of STING/TBK1/IRF3 trimer in endocrine‐resistant breast cancer." (PMID 39023171, 2024). "Our results show that the TBK1‐dependent activation of IRF3 is blunted in endocrine‐resistant breast cancer cells, thereby resulting in the suppression of cGAS‐STING signaling to mediate the endocrine resistance." (PMID 39023171, 2024). "In conclusion, our findings highlight how the PARP7-FRA1 axis regulates IRF1- and, consequently, IRF3-mediated cell intrinsic apoptosis signaling in lung and breast cancer cells." (PMID 38011562, 2023). "In breast cancer cells, IRF3 and MyD88 mRNAs were detected while IRF1 and IRF7 mRNAs were upregulated." (PMID 35737804, 2022). "Known to regulate cytokine secretion via NFκB and IRF3, the kinase is also a breast cancer oncogene, overexpressed in a variety of tumours." (PMID 32783398, 2020). "Furthermore, we analyzed the prognostic value of combining p‐AKT1 and nuclear IRF3 protein levels in ER+ HER2– breast cancer patients." (PMID 39023171, 2024). "A positive correlation was found between the expression of STING and its target gene IRF3 in breast cancer MSCs, indicating the activation of STING signaling in breast cancer MSCs." (PMID 38638003, 2024). "Multivariate Cox regression analysis showed that the p‐AKT1/nuclear IRF3 score was an independent prognostic factor for the DFS and OS of ER+ HER2– breast cancer patients." (PMID 39023171, 2024). "Collectively, our findings suggest that PARP7 inhibition induces IRF1- and IRF3-dependent apoptosis by promoting the degradation of FRA1 in FRA1-driven lung and breast cancer cell lines." (PMID 38011562, 2023). "Chemical inhibition of cGAS or TBK1 led to significantly reduced production of the IRF3 target CXCL10 in 66cl4 cells, indicating that the cGAS-STING-TBK1 pathway is important for IFN-I expression in the metastatic mouse breast cancer cells." (PMID 36882786, 2023). "We quantified phosphorylated and therefore transcriptionally active IRF3 and IRF7 in mammary carcinoma cells using western blots." (PMID 35737804, 2022). "IRF3 was not regulated, while IRF7 was upregulated in mammary carcinoma cells (p < 0.05)." (PMID 35737804, 2022).
myocardial infarction (16 papers, 2018 to 2025). Gross necrosis of the myocardium, as a result of interruption of the blood supply to the area, as in coronary thrombosis. "Both deletion of the Irf3 and Ifnar genes, the latter encoding the interferon α and β receptor subunit 1, affords salubrious effects in mouse models of myocardial infarction and heart failure." (PMID 40180542, 2025). "This is perhaps best exemplified by a report describing the role of IRF3 and type I IFNs in the response to myocardial infarction (MI)." (PMID 38665231, 2024). "The PorSignDB myocardial infarction signatures thus provide additional evidence of IRF3 as a driver of heart failure in response to myocardial infarction." (PMID 30458705, 2018). "In this study, interferon regulatory factor 3 (IRF3) knockout mice (IRF3−/−) showed improved cardiac function and limited heart failure post myocardial infarction." (PMID 30458705, 2018). "Consistent with the pathogenic role of activation of the CGAS-STING1 pathway, deletion of the Mb21d1, Sting1, or Irf3 gene abrogated the induction of the interferon 1 response and improved survival and cardiac remodeling in a mouse model of myocardial infarction." (PMID 40180542, 2025). "Deletion of the Irf3 or Ifnar gene afforded a near complete survival postmyocardial infarction, a finding that, if replicated in independent experiments, would render IRF3 and its receptors as very attractive therapeutic targets in myocardial infarction." (PMID 40180542, 2025). "In the model of myocardial infarction, suppression of IRF3-dependent signaling leaded to reduced levels of cardiac inflammatory cytokines and decreased inflammatory cell infiltration, apart from relieving left ventricular dilation and improving cardiac function." (PMID 34749750, 2021). "Accordingly, permanent coronary ligation in mice, a model of myocardial infarction, by releasing the self-DNA activates the CGAS-STING1 pathways, provoked phosphorylation of IRF3 and induced expression of the type I interferon response genes." (PMID 40180542, 2025). "An experimental study using a lipopolysaccharide-induced myocardial infarction mouse model with sepsis observed a notable increase in STING and p-IRF3 expression." (PMID 38803502, 2024). "A recent study showed that ischemic cell death and uptake of cell debris by macrophages in the heart induce activation of IRF3 and IFNI production, which plays a critical role in myocardial infarction." (PMID 32719713, 2020). "Last, over-active IRF3 in macrophages and enhanced production of type I IFN resulted in fatal inflammatory response to myocardial infarction while Irf3−/− mice were protected from myocardial infarction." (PMID 30515152, 2018). "Interestingly, post myocardial infarction TLR and IRF gene expression was almost exclusively increased in the infarct zone after myocardial ischemia (Tlr2, Tlr3, Tlr6, Tlr7, Tlr9, Irf3, Irf7)." (PMID 29538462, 2018). "When comparing the myocardial transcriptomes of wild type (wt) with cardioprotective IRF3−/− knockout mice in GSEA, PorSignDBs myocardial infarction tissue signatures were induced (UP), while non-infarcted healthy control heart tissue signatures were suppressed (DN)." (PMID 30458705, 2018).